IL6 (interleukin 6)
Diseases named in the same sentence as IL6 in open-access papers (continued):
Sharing a sentence is not in itself a finding about the gene and the disease.
VEXAS syndrome (13 papers, 2022 to 2025). An adult-onset inflammatory disease that affects only males and is caused by somatic, not germline, mutations. "Upregulation of expression of the gene encoding IL-6 in patients with VEXAS syndrome and its confirmation in a zebrafish model suggest that targeted therapy to block the IL-6 pathway may be an effective treatment." (PMID 37501758, 2023). "Overall, pending better therapies, anti-IL-1 and anti-IL-6 bDMARDs, along with JAKis, represent an opportunity for patients with VEXAS syndrome, albeit careful monitoring is essential to control disease activity and ensure treatment safety." (PMID 40046741, 2025). "Treatment approaches for the inflammatory manifestations of VEXAS syndrome have included broad-acting corticosteroids, as well as specific inhibitors of IL-1, IL-6, and JAK/STAT signaling." (PMID 41178709, 2025). "The persistent inflammatory environment in VEXAS syndrome is driven by markedly elevated levels of proinflammatory cytokines, notably interleukin-6 (IL-6), tumor necrosis factor-alpha (TNF-α), and interferon-alpha (IFN-α)." (PMID 40563745, 2025). "This critical mini-review explores JAK inhibitors and IL-6 inhibitors, contributing to the ongoing academic discourse on VEXAS syndrome." (PMID 39289602, 2024). "Current research on VEXAS syndrome reveals numerous unresolved questions regarding the clinical use of IL-6 inhibitors and JAK inhibitors." (PMID 39289602, 2024). "Although there is currently no further research elaborating on the specific mechanistic role of IL-6 in VEXAS syndrome, IL-6 inhibitors can still be considered as a potential therapeutic option." (PMID 39289602, 2024). "We describe the clinical course of a VEXAS syndrome patient with a somatic UBA1 variant who was treated with an oral steroid and anti-IL-6 therapy (tocilizumab) that lead to the resolution of the systemic symptoms." (PMID 36544501, 2022). "Unsupervised principal components analysis (PCA) separated patients with VEXAS syndrome from the other groups on dimension 2, driven by inflammatory cytokines (IL-6, IL-18), IL-1 receptor antagonist (IL-1RA) and myelomonocytic markers (calprotectin and galectin-3)." (PMID 38291039, 2024). "In fact, high serum levels of IL-6 have been observed in patients with VEXAS syndrome." (PMID 36544501, 2022). "IL-6 targeting therapies have been used in the treatment of autoinflammatory conditions and may provide improvements in suppressing inflammation in patients with VEXAS syndrome." (PMID 40287866, 2025). "We included patients with VEXAS syndrome who received treatment with azacitidine, JAK inhibitors, IL-6 inhibitors, anti-IL-1, or anti-TNF agents." (PMID 40287866, 2025). "The analysis of the peripheral blood from patients with VEXAS syndrome showed highly activated inflammatory signatures in multiple pathways, including tumor necrosis factor (TNF), interleukin-6 (IL-6), and interferon-γ." (PMID 37501758, 2023). "Targeted agents, including anti-IL-1 (anakinra and canakinumab), anti-IL-6 (tocilizumab), anti-tumor necrosis factor α (TNF-α) (adalimumab, infliximab, and etanercept), and Janus kinase inhibitors, have been proposed as possible treatments for VEXAS syndrome." (PMID 36544501, 2022). "Since immunologic studies of patient samples and zebrafish models in VEXAS syndrome demonstrated upregulation of multiple cytokine signatures including TNF, IL-6 and IFN-γ, a broad therapeutic approach could be beneficial rather than the specific blockade of single cytokines." (PMID 40124776, 2025). "While IL-6 inhibitors and JAK inhibitors appear effective in controlling inflammation, as evidenced by the improvement in symptoms such as skin lesions and edema, as well as laboratory indicators, they seem less effective in addressing the hematological involvement in VEXAS syndrome." (PMID 39289602, 2024).
VEXAS syndrome (continued). "Mutant myeloid cells are believed to drive the inflammation in patients with VEXAS syndrome, as analyses have revealed activated inflammatory pathways consistent with myeloid-induced inflammation, including tumor necrosis factor (TNF), interleukin-6 (IL-6), and interferon-gamma (INF-gamma)." (PMID 36879894, 2023).
age (12 papers, 2017 to 2025). A temporal measurement of the time period elapsed since an identifiable point in the life cycle of an organism. "Among the SASP components, IL-6 is a possible candidate for a relevant inflammatory factor in age-related bone loss." (PMID 37891477, 2023). "Inflammatory markers such as CRP and IL-6 are reported to be associated with decreased muscle mass and strength, and the reduction of inflammation is believed to directly or indirectly ameliorate age-related muscle loss." (PMID 33882026, 2021). "Thus, the JAK/STAT pathway is involved in regulating cytokine production, and the JAK inhibitor ruxolitinib inhibits secretion of SASP factors (IL-6, IL-8, and PAI-1) and alleviates age-related bone loss." (PMID 37891477, 2023). "On the other hand, IL-6 is a component of age-related chronic low-grade inflammation." (PMID 36311511, 2022). "At baseline, at 0 months of treatment of either AGE or placebo, the IL-6 concentration was 4.762 ± 0.701 ng/L in the AGE group and 4.173 ± 0.653 ng/L in the placebo group (p > 0.05)." (PMID 33868439, 2021). "After 12 months of treatment, the IL-6 concentration was 3.754 ± 0.493 ng/L in the AGE group and 4.573 ± 0.461 ng/L in the placebo group (p > 0.05)." (PMID 33868439, 2021). "Recent evidence suggests that age-related chronic inflammation is correlated with elevated levels of circulating biomarkers, such as TNF-alpha, IL-1beta, IL-6, COX-2, iNOS." (PMID 39286235, 2024). "It no longer surprises that age-related chronic conditions are often characterized by a low-grade augmentation of circulating titers of proinflammatory mediators, which includes IL-6." (PMID 33489375, 2020).
basal cell carcinoma (12 papers, 2010 to 2024). A carcinoma involving the basal cells. "To explore the association between the IL-6 -174 G/C polymorphism and the risk of basal cell carcinoma (BCC) in a Chinese population, we performed a case-control study involving 265 BCC patients and 341 controls." (PMID 32859764, 2020). "The associations between IL-6 -174 G/C polymorphism and clinical characteristics of basal cell carcinoma." (PMID 32859764, 2020). "Stratified analyses between IL-6 -174 G/C polymorphism and the risk of basal cell carcinoma." (PMID 32859764, 2020). "Vascular endothelial growth factor A (VEGF-A) and interleukin-6 (IL-6) expressions in basal cell carcinoma (BCC) punch biopsy samples from head and neck." (PMID 37902813, 2023). "A possible role for IL-6 in the progression of cervical lesions has already been observed in the human basal cell carcinoma (BCC-1/KMC) cell line." (PMID 26990868, 2016). "In addition, the overexpression of IL-6 induced Mcl-1 overexpression and inhibited apoptosis in basal cell carcinoma." (PMID 39272918, 2024). "Furthermore, it has been reported that overexpression of IL-6 enhances the tumorigenic activity of basal cell carcinoma cells by inhibiting apoptosis and promoting angiogenesis." (PMID 31396215, 2019). "Also, the repression of HPV18 E6 and E7 in basal cell carcinoma cells reduced IL-6 expression levels." (PMID 31396215, 2019). "CXCL12 has been reported to increase IL‐6 expression in fibroblasts and human basal cell carcinoma, while AMD3100 inhibits the CXCL12‐induced IL‐6 expression." (PMID 35363937, 2022). "IL-6 can also be produced directly by cancer cells, such as in basal cell carcinoma (nonmelanoma skin cancer) where IL-6 is secreted through the HH/ GLI1 pathway via STAT3 activating IL-6." (PMID 33691728, 2021).
bladder tumor (12 papers, 2012 to 2024). "Recently, SMARCB1 (switch/sucrose nonfermentable-related matrix-associated actin-dependent regulator of chromatin subfamily B member 1), which encodes INI-1 (integrase interactor 1) loss, was found to drive bladder tumor progression via activation of the IL6/STAT3 axis." (PMID 39273033, 2024). "For instance, bladder tumor cells release IL-6, IL-8, and other molecules, resulting in tumors with increased vascularization and infiltration." (PMID 38338162, 2024). "Altogether, we suggest that the liposome-derived internalization of BCG-CWS into bladder tumor tissues increases IL-6 production and CD4 infiltration, thereby increasing the antitumor efficacy." (PMID 31817179, 2019). "Overall, the low levels of NOTCH/IL-6 and immune-related genes indicate profound dysregulation of tumor-suppressive pathways in bladder tumors." (PMID 29242529, 2017). "In the present study, we examined the correlation between Treg/TAM and IL6 in the bladder tumor microenvironment." (PMID 29048388, 2017). "Downstream IL-6 signaling JAK1, STAT3, and SOCS3 were consistently upregulated in the same bladder tumors with low IL-6 levels suggesting IL-6 independent activation of the JAK1/STAT3 pathway." (PMID 29242529, 2017). "Meanwhile, targeting IL-6 might be a promising therapeutic target in BC because IL-6 inhibition can attenuate bladder tumor growth and invasive capability." (PMID 33494738, 2021). "Data revealed that inhibiting IL-6 resulted in decreased bladder tumor growth in vitro and in vivo." (PMID 23637926, 2013). "In addition, the importance and role of cytokines, including IL-2, IL-12, IFN-gamma, IL-6, and IL-15, in inhibiting the incidence and growth of bladder tumors has been established." (PMID 22962576, 2012). "Furthermore, although IL-6 induces the Th2 response, which might be controlled by the presence of IFN-γ and the absence of IL-418, IL-6 also up-regulates the fibronectin α5β1 receptor, which is involved in the interaction of BCG with the urothelium, which inhibits bladder tumor cell proliferation." (PMID 30305693, 2018).
Brain atrophy (12 papers, 2012 to 2025). Partial or complete wasting (loss) of brain tissue that was once present. "A recent study by Hanning and colleagues found that brain atrophy in the elderly is associated with higher IL-6 and IL-8 circulating levels, suggesting a role for systemic inflammation in the brain atrophy pathogenesis." (PMID 29156608, 2017). "Additionally, connections between genetic variants of IL-6 and the volume of the hippocampus were analyzed using voxel-based morphometry indicating that the IL-6 allele has a significant role in the development of brain atrophy." (PMID 25025046, 2014). "In addition, higher circulating levels of IL-6 have been associated with MRI markers of global brain and hippocampal atrophy, suggesting a link between blood IL-6 levels and AD-like brain atrophy patterns." (PMID 39800457, 2025). "A relevant study revealed that plasma levels of peripheral inflammatory markers, such as BAFF/TNFSF13B, IL-4, IL-6, IL-17A, and TNF-α, exhibited associations with patterns of brain atrophy, brain hypometabolism, and clinical measures of disease severity and functional status in bvFTD." (PMID 37762113, 2023). "In addition, first studies on the association between IL-6 and brain volume suggested a role of increased serum levels of IL-6 in brain atrophy during normal aging in conjunction with other cytokines." (PMID 22695063, 2012). "Patients with CHF and CD have increased levels of pro-inflammatory cytokines (interleukin-6—IL-6, tumor necrosis factor—alpha—TNF-α), and high levels of total plasma homocysteine that stimulate apoptosis of neural cells, with brain atrophy." (PMID 41149261, 2025).
cervical (12 papers, 2013 to 2025). "The present study was designed and implemented to compare the cervical levels of IL-6 and IL-8 in the patients with premalignant and malignant cervical lesions and normal women and also to explore its association with cervical premalignant lesions." (PMID 33906316, 2021). "Together, these data demonstrate that p65 and IL-6 levels are increased in HPV associated cervical disease." (PMID 31226168, 2019). "Persistent infection with high-risk HPV strains, a known driver of cervical carcinogenesis, induces inflammatory responses that may contribute to increased IL-6 expression." (PMID 41561529, 2025). "We analysed cervical liquid-based cytology samples from a cohort of HPV16+ patients representing the progression of disease development (CIN1-CIN3) and compared this to HPV- normal cervical tissue to explore the role of IL-6 in cervical disease." (PMID 31226168, 2019). "Although many studies have focused on IL-6 and its involvement in cervical carcinogenesis, there are few reports on IL-6R and its implication in CC." (PMID 31396215, 2019). "We previously demonstrated increased STAT3 phosphorylation in cervical disease and we now demonstrate a similar link between IL-6 levels and cervical disease." (PMID 31226168, 2019). "This theory is supported by other authors, asserting that IL-6 and IL-8 may have diagnostic utility to discriminate between OSCC and healthy patients, noting that IL-6 is elevated in cases of stages T3 and T4 and those stages in which there is cervical metastasis." (PMID 36330456, 2022). "Furthermore, increased cervical IL-1β, IL-6, and IL-8 were detected among HIV positive women with cervicitis." (PMID 35583346, 2022).
corneal infection (12 papers, 2009 to 2025). A viral or bacterial infectious process affecting the cornea. "Corneal infection and trauma are often associated with significant IL-6 increases." (PMID 30701198, 2019). "Patients with severe corneal infection (n = 10) exhibited slightly but significantly higher tear concentrations of IL-6 compared to the controls (P = 0.0303) (corrected P = 0.2424)." (PMID 38694515, 2024). "A higher concentration of IL-6 was observed in the samples of corneal infection patients compared to the control samples (P = 0.0117; corrected P = 0.0936), but the difference was not statistically significant (P > 0.05)." (PMID 38694515, 2024). "qPCR detection of corneal ulcers from patients and infected epithelial cell lines revealed that the mRNA expression of Toll-like receptors, IL-1β, IL-6, and IL-8 was elevated." (PMID 35578336, 2022). "IL-6 is a potential mediator of intraocular inflammation, and several evidence indicate that it plays an important multifunctional role in corneal infection and inflammation." (PMID 29673332, 2018). "Pro-inflammatory cytokines like IL-1, IL-6 and TNF-α produces by keratocytes is also an important factor causing corneal ulcer." (PMID 28448563, 2017). "Effective recruitment of neutrophils into the cornea is dependent on the production of IL-6, and IL-6 has been demonstrated to be a protective factor in corneal infection." (PMID 19590756, 2009). "Proinflammatory cytokines such as IL-1β and IL-6 contribute to corneal ulceration." (PMID 22219637, 2011). "Apart from the retina, studies on corneal infections have also similar findings where they have observed that P. aeruginosa signal the NF-κB system leading to expression and secretion of proinflammatory cytokines, IL-6 and IL-8, both of which are important in regulating PMN infiltration." (PMID 35046947, 2021). "Specifically, glutamine treatment effectively attenuates endotoxin-induced canine corneal ulceration by suppressing the NF-κB pathway, alongside its downstream TNF-α and IL-6 signaling." (PMID 39837870, 2025). "The concentration of IL-6 was not significantly higher in corneal infection samples than in the controls after applying the Bonferroni correction for multiple comparisons (P = 0.0067) (corrected P = 0.0536)." (PMID 38694515, 2024). "Furthermore, IL-6 was significantly detected in the tears of patients with severe corneal infections compared to healthy volunteers, but it was not statistically significant after the Bonferroni correction." (PMID 38694515, 2024).
demyelinating disease (12 papers, 2013 to 2024). A broad group of disorders that affect the myelin sheaths that cover the neurons. "Therefore, the excessive production of IL-6 and IL-1β appears to be mainly responsible for the development of demyelinating disease via preferential differentiation of pathogenic Th17 cells." (PMID 34067536, 2021). "Excessive levels of cytokines, particularly IL-6 and IL-1β, facilitate the generation of pathogenic Th17 immune responses to viral antigens and autoantigens, leading to TMEV-induced demyelinating disease." (PMID 37153539, 2023). "In fact, the pro-inflammatory cytokines IL-6 and IL-1β have critical roles in the pathogenic immune responses leading to TMEV-induced demyelinating disease in SJL/J mice." (PMID 35805128, 2022). "IL-6 and IL-1β play particularly important roles in the pathogenic T cell responses in the development of TMEV-induced demyelinating disease." (PMID 34067536, 2021). "Because anti-TNF therapy can induce and worsen demyelinating diseases, anti-IL-6 therapy is a potential treatment for patients with RA complicated by MS." (PMID 25216562, 2014). "This is consistent with the fact that TMEV infection and replication are greater in the cells of susceptible mice and that excessive TLR signal and cytokine production, including IL-1β, IL-6, and TGFβ, further promotes the pathogenesis of demyelinating disease." (PMID 37153539, 2023). "In comparison, few studies have reported anti-IL-6 therapy in demyelinating disorders." (PMID 25216562, 2014). "Studies have investigated the possible usefulness of IL-6 as a biomarker of CNS diseases, especially in the context of demyelinating diseases; however, the small size of the studied samples and the inclusion of restricted neurological conditions limit its usefulness in clinical practice." (PMID 24015240, 2013). "Failure to clear the virus from infected cells can result in persistent production of IL-6 and TNF-α, which contribute to demyelinating diseases." (PMID 35805128, 2022). "IL-6 participates in initiating and amplifying the pathogenesis of TMEV-induced demyelinating disease." (PMID 34067536, 2021). "Therefore, functional inhibition of key inflammatory cytokines, such as IL-6, IL-1β, and/or IL-17, which are critical for the development of pathogenic T cell responses and viral persistence, may prevent the pathogenesis of TMEV-induced demyelinating disease." (PMID 34067536, 2021). "In fact, mice lacking IL-6 signaling fail to develop demyelinating disease following TMEV infection." (PMID 34067536, 2021). "Among the important cytokines, the effects of TNF-α, IL-1β, IL-6, IFN-α/β, and prostaglandin E2, which either alter the type of T cell responses or inhibit immune responses in the development of demyelinating disease, have been investigated." (PMID 33086489, 2020). "Because the levels of IL-6 and T cells in the CNS are known to play important roles in the pathogenesis of TMEV-induced demyelinating disease, the signals downstream of the NLRP3 inflammasome are likely to be involved in the pathogenesis of TMEV-induced, immune-mediated demyelinating disease." (PMID 28445497, 2017). "More recently, concentrations of interleukin-6 (IL-6) and of the soluble IL-6 receptor (sIL-6R) were found to be higher in the CSF of NMO patients than of MS patients, and these may prove to be useful markers for differentiating NMO from other demyelinating diseases." (PMID 24272588, 2014).